FERMT1 (FERM domain containing kindlin 1)
Description:
Involved in cell adhesion. Contributes to integrin activation. When coexpressed with talin, potentiates activation of ITGA2B. Required for normal keratinocyte proliferation. Required for normal polarization of basal keratinocytes in skin, and for normal cell shape. Required for normal adhesion of keratinocytes to fibronectin and laminin, and for normal keratinocyte migration to wound sites. May mediate TGF-beta 1 signaling in tumor progression.
Synonyms: C20orf42; KIND1; URP1; FLJ20116; UNC112A; DTGCU2
Tractability: Antibody: UniProt places it where antibodies can reach, with medium confidence; its Gene Ontology location is reachable by antibodies, with medium confidence. PROTAC: ubiquitination databases record sites on it.
Gene: Protein-coding gene on chromosome 20 (6,070,288 to 6,123,644, reverse strand). Ensembl gene ENSG00000101311.
Subcellular location: Cytoplasm, cytoskeleton; Cell junction, focal adhesion; Cell projection, ruffle membrane
Gene Ontology:
Molecular function: integrin binding; actin filament binding
Biological process: cell adhesion; establishment of epithelial cell polarity; keratinocyte migration; keratinocyte proliferation; positive regulation of integrin activation; positive regulation of wound healing, spreading of epidermal cells; cell-matrix adhesion; basement membrane organization; integrin-mediated signaling pathway; negative regulation of canonical Wnt signaling pathway; negative regulation of gene expression; negative regulation of protein import into nucleus; negative regulation of stem cell proliferation; negative regulation of timing of anagen; positive regulation of cell adhesion mediated by integrin; positive regulation of cell migration; positive regulation of cell-matrix adhesion; positive regulation of transforming growth factor beta production; positive regulation of transforming growth factor beta receptor signaling pathway
Cellular component: cell junction; cell periphery; cytoplasm; cytosol; focal adhesion; cytoskeleton; ruffle membrane
Genetic constraint (gnomAD): Loss-of-function variants: 47 observed, 68.79 expected, observed/expected ratio (o/e) 0.68, 90% interval 0.54 to 0.87. The upper end of that interval is the gene's LOEUF score, 0.87, which puts it in group 3 of 6, group 1 being the genes least tolerant of losing a copy. Missense variants: 602 observed, 731.68 expected, observed/expected ratio (o/e) 0.82, 90% interval 0.77 to 0.88. Synonymous variants: 239 observed, 270.27 expected, observed/expected ratio (o/e) 0.88, 90% interval 0.8 to 0.98.
Gene-disease validity (ClinGen):
ClinGen rates the evidence that FERMT1 causes each of these diseases.
Kindler syndrome (autosomal recessive): Definitive. Kindler syndrome (KS) is the fourth major type of epidermolysis bullosa (EB), besides simplex, junctional and dystrophic forms, and is characterized by skin fragility and blistering at birth followed by development of photosensitivity and progressive poikilodermatous skin changes.
Homologues: Orthologues: chimpanzee FERMT1 (99% identical), macaque FERMT1 (98% identical), dog FERMT1 (93% identical), pig FERMT1 (91% identical), rabbit FERMT1 (90% identical), guinea pig FERMT1 (89% identical), rat Fermt1 (89% identical), mouse Fermt1 (88% identical), tropical clawed frog fermt1 (76% identical), zebrafish fermt1 (66% identical), Drosophila melanogaster Fit1 (44% identical), Caenorhabditis elegans unc-112 (44% identical), and 1 more. Paralogues in human: FERMT2 (63% identical), FERMT3 (55% identical).
Diseases named in the same sentence as FERMT1 in open-access papers:
FERMT1 is named in the same sentence as 62 diseases in open-access papers, as found by Europe PMC text mining. Sharing a sentence is not in itself a finding about the gene and the disease. The quoted sentences say what the papers report.
Kindler syndrome (32 papers, 2008 to 2025). "For example, Kindler syndrome, a form of skin disease, is caused by mutations in the kindlin gene (FERMT1)." (PMID 40960860, 2025). "This study aims to ascertain the potential pathogenicity of a FERMT1 variant identified in a Chinese patient and to explore the phenotypic and molecular genetic characteristics of all reported cases of Kindler Syndrome in the Chinese population." (PMID 39309641, 2024). "Mutations in the FERMT1 (Four point one Ezrin Radixin and Moesin − 1) gene are the main cause of Kindler syndrome, which lead to premature termination of translation and loss of the kindlin-1 protein." (PMID 37106609, 2023). "Mutations in KINDLIN-1, also known as FERMT1, result in kindler syndrome, an IEI that manifests primarily as a skin disorder, characterized by acral blistering as neonates and poikiloderma with age." (PMID 36248828, 2022). "Defects in FERMT1 cause Kindler syndrome (KS), a genetic disease that is characterized by fragile skin and an increased risk of squamous cell carcinoma." (PMID 35144617, 2022). "Mutations in FERMT1 (also known as KIND1), encoding the focal adhesion protein kindlin-1, cause Kindler syndrome (KS)." (PMID 34512655, 2021). "A deficiency or defect of FERMT1 is associated with Kindler syndrome, a skin disease characterized by cutaneous blistering, atrophied skin, photosensitivity, progressive poikiloderma in sun-exposed areas and lethal neonatal intestinal epithelial dysfunction." (PMID 32575800, 2020). "Kindler syndrome is an autosomal recessive genodermatosis that results from mutations in the FERMT1 gene encoding t kindlin-1." (PMID 30248333, 2019). "The original nomenclature of the family originates from a rare congenital skin disease in humans named Kindler syndrome caused by mutations in the Kindlin-1 (Fermitin family homolog 1; FERMT1) gene." (PMID 30382829, 2018). "Kindlin-1 (also known as FERMT1) is highly expressed in the skin and other tissues, whose deficiency and mutation can cause Kindler Syndrome." (PMID 30386175, 2018). "Loss-of-function of Fermt1 is associated with Kindler syndrome, an autosomal recessive disorder characterized by skin atrophy and blistering." (PMID 21949838, 2011). "Mutations in FERMT1, coding for the Kindlin-1 protein, cause Kindler Syndrome in humans, characterized by skin blistering, atrophy, and cancer." (PMID 19057668, 2008). "Kindler Syndrome (KS), characterized by transient skin blistering followed by abnormal pigmentation, skin atrophy, and skin cancer, is caused by mutations in the FERMT1 gene." (PMID 19057668, 2008). "Kindler syndrome is caused by loss-of-function mutations in FERMT1, which encodes Kindlin-1." (PMID 40806555, 2025). "In addition, Kindler syndrome (OMIM #173650) due to FERMT1 gene mutations, and poikiloderma with neutropenia type Clericuzio (OMIM #604173), associated with biallelic mutations in USB1 gene." (PMID 35328050, 2022). "Similarly, in Kindler syndrome, a familial blistering disease, inactivating mutations in the FERMT1 gene, which encodes Kindlin-1, result in loss of epidermal attachment and integrity, as well as susceptibility to cutaneous squamous cell carcinomas." (PMID 29568383, 2018). "Kindler syndrome (KS) is a rare genodermatosis resulting from loss-of-function mutations in FERMT1, the gene that encodes Kindlin-1." (PMID 38982038, 2024). "Keratinocytes from patients with Kindler syndrome who have loss-of-function mutations in FERMT1, the gene that encodes kindlin-1, increase their IL-6 production post-UV exposure." (PMID 39641590, 2024). "As a member of Kindlins, fermitin family member 1 (FERMT1, also known as Kindlin-1) is related to Kindler syndrome (KS), a genetic disorder that mainly affects the skin and intestine." (PMID 36981005, 2023). "Deleting FERMT1 leads to Kindler syndrome characterized by skin abnormalities, which is related to an increased risk of developing squamous cell carcinomas." (PMID 35144617, 2022).
Kindler syndrome (continued). "Null variants in FERMT1 are the most common defect in Kindler syndrome, a rare condition of epithelial fragility caused by lack of kindlin-1, which anchors the actin cytoskeleton to the plasma membrane, and is an important cause of monogenic IBD37–39." (PMID 40666361, 2025). "Finally, Kindler syndrome is an autosomal recessive disease affecting the protein kindlin-1 (FERMT1), leading to mixed cleavage planes." (PMID 35052793, 2022). "In Kindler syndrome, mutations in FERMT1 lead to lack of Kindlin 1 and an induction of inflammatory response in keratinocytes via paracrine communication." (PMID 30565237, 2019). "Kindler Syndrome (KS; OMIM:173650) is a rare, recessive genodermatosis caused by mutations in the FERMT1 gene (C20ORF42/KIND1)." (PMID 19057668, 2008). "RM has since been documented in EBS, JEB generalized intermediate, RDEB, DDEB, and Kindler syndrome, implicating COL17A1, KRT14, LAMB3, COL7A1, and FERMT1 genes, and the topic of prior reviews." (PMID 35052793, 2022).
breast carcinoma (12 papers, 2012 to 2024). "FERMT1 regulates TGF-β-induced EMT in breast cancer cell lines to promote breast cancer development and lung metastasis." (PMID 39261464, 2024). "We used a syngeneic model in which Fermt1 had been deleted in the Met-1 murine breast cancer cell line (Kin1-NULL) and to which either wild type Kindlin1 (Kin1-WT), or a mutant that is unable to bind β-integrin (Kin1-AA) were reintroduced." (PMID 36883731, 2023). "FERMT1 is overexpressed in many cancers, including colon cancer, breast cancer, lung cancer, hepatocellular carcinoma, and pancreatic cancer." (PMID 35144617, 2022). "FERMT1 expression was correlated with metastasis-free survival in breast cancer, and silencing of FERMT1 inhibited lung metastasis of breast cancer." (PMID 34814915, 2021). "ANP32E along with desmocollin 2 (DSC2), UDP glycosyltransferase 8 (UGT8), Integrin subunit beta 8 (ITGB8) and Fermitin family member 1 (FERMT1) is found to predict lung metastasis of breast cancer patients and has been used as prognostic marker." (PMID 32257110, 2020). "Analysis of a publicly available human breast cancer data set (METABRIC), demonstrated a small but significant correlation between FERMT1 (Kindlin-1) and CD274 (PD-L1) gene expression." (PMID 36883731, 2023).
colon carcinoma (11 papers, 2008 to 2024). "Several studies have implicated FERMT1 in colon cancer, nasopharyngeal carcinoma, gastric cancer, oral squamous cell carcinoma, and pancreatic cancer." (PMID 38976072, 2024). "Fermitin family member 1, FERMT1, encoded protein is involved in integrin signalling and linkage of the actin cytoskeleton to the extracellular matrix and has been shown to be significantly over-expressed in colon cancer." (PMID 32024004, 2020). "In the context of colon cancer, there is compelling evidence linking FERMT1 expression to tumor progression, metastasis, and an unfavorable prognosis." (PMID 38976072, 2024). "The overexpression of FERMT1 was found in multiple tumors such as colon cancer, gastric cancer, oral squamous cell carcinoma, and nasopharyngeal carcinoma, and has been associated with metastasis and poor prognosis." (PMID 36981005, 2023). "A previous study found that FERMT1 expression was increased in colon cancer, which was an independent prognostic factor for poor overall survival, and FERMT1 promoted colon cancer metastasis." (PMID 34814915, 2021). "FERMT1, which encodes the kindlin-1 protein that belongs to a family of focal adhesion proteins, activates EMT to promote colon cancer metastasis both in vitro and in vivo." (PMID 34814915, 2021). "FERMT1 promoted colon cancer metastasis and epithelial–mesenchymal transition progression via modulation of β-catenin transcriptional activity." (PMID 31850052, 2019). "Moreover, abnormal FERMT1 expression has been described in several cancers, including colon cancer, gastric cancer, oral squamous cell carcinoma and nasopharyngeal carcinoma." (PMID 36981005, 2023). "FERMT1 mediates the β-catenin/EMT signaling pathway to promote colon cancer metastasis." (PMID 34814915, 2021). "FERMT1 has been shown to interact directly with β-catenin and activated the Wnt/β-catenin signalling pathway by decreasing the phosphorylation level of β-catenin in colon cancer." (PMID 32024004, 2020).
pancreatic cancer (8 papers, 2016 to 2024). "In pancreatic cancer, FERMT1 has been identified as a methylation-driving gene to construct a nomogram model to predict overall survival." (PMID 36981005, 2023). "Microarray analysis of fresh tumor samples from human pancreatic cancer patients implanted into severely combined immunodeficient (SCID) mice revealed that FERMT1 mRNA was increased in patient-derived xenograft (PDX) tumors compared to normal mice." (PMID 36981005, 2023). "Meanwhile, more evidence has suggested that FERMT1 has a role in many types of tumors, such as skin cancer, lung cancer, bladder cancer, and pancreatic cancer." (PMID 35144617, 2022). "FERMT1 expression was also increased in pancreatic cancer, and FERMT1 promoted pancreatic cancer metastasis." (PMID 34814915, 2021). "Here, our results indicated that patients with high FERMT1 expression were more sensitive to Palbociclib, AM-5992 and TAE-226, which could serve as drug candidates for combination therapy to improve pancreatic cancer treatment." (PMID 36981005, 2023). "To date, FERMT1 changes have not previously been directly shown in pancreatic cancer." (PMID 32024004, 2020).
gastric cancer (7 papers, 2020 to 2024). A primary or metastatic malignant neoplasm involving the stomach. "Higher FERMT1 expression was found in human gastric cancer tissues and has been significantly associated with poor overall survival; FERMT1 enhanced gastric cancer metastasis and EMT by activating the NF-κB pathway." (PMID 34814915, 2021). "Similarly, FERMT1 overexpression has been associated with aggressive behavior and poor clinical outcomes in gastric cancer and oral squamous cell carcinoma." (PMID 38976072, 2024). "FERMT1, as an oncogene, promotes the degradation of IκBα, thereby activating NF-κB signaling and promoting gastric cancer." (PMID 33842346, 2021). "In vitro and in vivo experiments indicated that knockdown of FERMT1 inhibited the proliferation, invasion, metastasis, and epithelial-mesenchymal transition of gastric cancer cells." (PMID 32723205, 2020). "Clinical data analysis indicated that the expression of FERMT1 correlated with the overall survival of gastric cancer patients." (PMID 32723205, 2020). "Mechanistically, FERMT1 was found to activate NF-κB signaling by promoting the degradation of IκBα, thereby promoting gastric cancer." (PMID 32723205, 2020). "In addition, a study demonstrated that FERMT1 promoted EMT in gastric cancer cells by activating the NF-κB signaling pathway via cell and animal experiments." (PMID 35144617, 2022). "Upregulation of FERMT1 promotes the progression of gastric cancer." (PMID 35557945, 2022). "We found that FERMT1 was overexpressed in gastric cancer tissues compared with normal tissues." (PMID 32723205, 2020). "However, the function and regulatory mechanism of FERMT1 in gastric cancer remain unknown." (PMID 32723205, 2020).
lung carcinoma (7 papers, 2012 to 2024). "Despite lung cancer being a prevalent and lethal tumor with poorly understood underlying pathological mechanisms, FERMT1, belonging to the Kindlin protein family, is a regulator of integrin activity." (PMID 38200443, 2024). "Nevertheless, the involvement of FERMT1 in the progression of lung cancer requires further exploration." (PMID 38200443, 2024). "Further studies also confirmed that FERMT1 regulates the invasion and migration of lung cancer through PKP3." (PMID 38200443, 2024). "Ultimately, an examination was conducted in the human normal lung epithelial cell BEAS-2B and four NSCLC cell lines, revealing that the transcription and expression levels of FERMT1 were elevated in lung cancer cells compared to BEAS-2B." (PMID 38200443, 2024).
skin atrophy (6 papers, 2008 to 2025). The degeneration and thinning of the epidermis and dermis. "Null mutations in the FERMT1 gene give rise to neonatal-onset skin atrophy and acute and fulminant intestinal epithelial dysfunction." (PMID 41142805, 2025). "In the present study we show that a null mutation in the Fermt1 gene gives rise to skin atrophy and an acute and fulminant, neonatal intestinal epithelial dysfunction." (PMID 19057668, 2008). "KS is an autosomal recessive genodermatosis resulting from loss-of-function mutations in FERMT1, the gene that encodes Kindlin-1 leading to skin atrophy, blistering, photosensitivity, hyper or hypo-pigmentation, increased light sensitivity as well as a high incidence of cSCC." (PMID 38982038, 2024).